IL6 (interleukin 6)
Diseases named in the same sentence as IL6 in open-access papers (continued):
Sharing a sentence is not in itself a finding about the gene and the disease.
tumor (continued). "Another miRNA, miR-33a, displayed its tumor-suppressive activity by suppressing IL-6-mediated tumor progression via binding Twist in GBC." (PMID 34944491, 2021). "These also secrete tumor growth factors, cytokines, chemokines, such as TGF-beta, vascular endothelial growth factor (VEGF), IL-6, IL-8, IL-12, and matrix metalloproteinases which induce angiogenesis, supporting tumor growth." (PMID 33924623, 2021). "Related to this, several regulators have been reported to mediate the activation of STAT3, including IL-6, which in fact can be produced by tumor cells." (PMID 34638305, 2021). "As a matter of fact, the presence of IL6 in the tumor microenvironment stimulates WM cell growth and the secretion of IgM protein." (PMID 33921415, 2021). "Through the secretion of factors such as interleukin 6 (IL-6) or interferon gamma (IFNγ), which are responsible for immune cell mobilization, they can indirectly suppress tumor progression." (PMID 33430277, 2021). "STAT3 signalling between tumour cells, immune cells and the tumour microenvironment is mediated by factors, including IL‐6, IL‐10 and VEGF." (PMID 33382511, 2021). "Shh signalling and Notch signalling in osteoblasts confer proliferative advantages to bone metastatic tumour cells through the production of interleukin (IL)-6." (PMID 35006432, 2021). "We found that CTX inhibits tumor-related cytokines, particularly IL-6, IL-8, HGF, TGF-β1, and IGFBP-1." (PMID 34822613, 2021). "The blockade of IL-6 signaling using an IL-6 receptor antibody reduced tumor development in an AOM/DSS mouse model." (PMID 33578830, 2021). "High levels of certain inflammatory cytokines like IL-6 in the tumor microenvironment can bind to membrane-bound receptor molecules (IL-6R) in tumor cells." (PMID 33980865, 2021). "Studies in neuroblastoma have demonstrated that tumor cells induce suppressive macrophage populations, which inhibit effector NK cells via secretion of IL-6 and TGF-β and thus dampen the efficiency of anti-GD2-targeted immunotherapy." (PMID 33917501, 2021). "VEGF, IL-6 and IL-10, which are usually overexpressed in TME, can activate STAT3 signaling, thereby inducing an immature tolerance phenotype in tumor-associated DCs and promoting tumor progression." (PMID 33935714, 2021). "Xenograft models confirmed that M2 macrophage-derived exosomal miR-155-5p reduced the ZC3H12B expression to upregulate IL-6, which consequently induced immune escape and tumor formation." (PMID 33718596, 2021). "In some reports, high interleukin-6 (IL-6) production promotes tumor growth by autocrine stimulation and tocilizumab, an IL-6 receptor antagonist, can control AFH growth." (PMID 34221525, 2021). "IL6 is an important inflammatory cytokine that has various functions in immune cell responses and tumor growth regulation." (PMID 34305997, 2021). "We chose serum TNF-α, IFN-β, and IL-6 as the investigated cytokines, which were secreted by the activated immune cells and essential factors to eliminate tumor cells." (PMID 34541546, 2021). "Here, we show that IL-6 controls a mechanistic switch between primarily cytotoxic cell death and immune-mediated clearance of tumor cells after genotoxic chemotherapy treatment." (PMID 34711820, 2021). "One the other hand, both C26 cell clones expressed IL-6 mRNA only in the presence of IL-1 in vitro, and mice bearing either of the clones expressed IL-1β mRNA at the tumor site." (PMID 33557173, 2021). "This is further supported by gene expression analysis, where CAFs isolated from Osm−/− tumours exhibited decreased inflammatory gene expression (e.g. Il6, Mmp3, Has2 and Osmr) but increased myofibroblast gene expression (e.g. Acta2, Itgav and Fn1)." (PMID 34921158, 2021). "On the other hand, the dual blockade of IL-6 and PD-L1 reduced tumor progression in an experimental model; therefore, a combination of ICIs and other agents can be a promising therapeutic strategy." (PMID 34063828, 2021).
tumor (continued). "In summary, the results presented here show that TAK1 promotes tumour propagation, can be activated by IL‐6 and binds to YAP in GCSCs." (PMID 34075691, 2021). "Interleukins such as IL-6, IL-17, or IL-23 contribute to tumor progression, and tumor necrosis factor (TNF)-α, transforming growth factor (TGF)-β, or IL-6 has a direct effect on the cell growth and survival rate." (PMID 34112142, 2021). "In our previous studies we showed that resveratrol (RV), a nutraceutical and caloric restriction mimetic, is a formidable enhancer of autophagy capable of counteracting the pro-invasive activity of IL-6 found in the tumor microenvironment." (PMID 34831435, 2021). "In a CCSPCre/LSL-KrasG12D mouse model of KRAS-driven NSCLC, IL6 induced the proliferation of tumor cells and facilitated an immunosuppressive microenvironment by enhancing the polarization of alternatively activated macrophages and recruitment of MDSCs." (PMID 34944848, 2021). "Deletion of tumor cell–derived IL-6 increased mouse survival, with median survival of 24 d in KPC IL6KO tumor mice compared with 17 d in KPC tumor mice (P = 0.001)." (PMID 33851955, 2021). "Blocking IL-6 impairs the growth of tumor, indicating the ability of IL-6 secreted by senescent cells in promoting cancer progression." (PMID 34458273, 2021). "In turn, tumor cells can also express or respond to IL‐6, leading to increased proliferation and invasion." (PMID 34459122, 2021). "We also noticed that the IL6 expression is higher in tumor tissues of children older than 18 months." (PMID 34790130, 2021). "We conclude that the growth-promoting and anti-apoptotic mechanisms activated by IL-6 are critically involved in Eμ-myc driven tumor initiation and progression, but the B cell intrinsic expression of STAT3 is not required." (PMID 33651821, 2021). "Tumor cells and reactive stroma are responsible for the synthesis of IL-6 which induces inflammation via Ras/Raf/MAPK, PI3K, or Src/YAP pathways through JAK." (PMID 34220337, 2021). "Our study reveals a new role for tumor-derived IL-6 in hijacking the HSPC differentiation program toward prometastatic MDPs that functionally differentiate into immunosuppressive monocytes to support the metastatic switch." (PMID 34140316, 2021). "The IL6/JAK/STAT3/SIGNALING pathway was considered as a potential mechanism of genomic instability to influence tumor progression." (PMID 34712264, 2021). "Similar to the findings observed in the genetically induced GBM model, pro-CD40 and anti-IL-6 monotherapy showed limited and moderate therapeutic effects on tumor growth and animal survival, respectively." (PMID 34103524, 2021). "SHH released by tumor cells is able to act on osteoblasts to increase their production of IL-6, which in turn promotes osteoclast differentiation during bone metastasis." (PMID 33731701, 2021). "In these xenografts, we enlightened the expression of both IL6 and the NF-kB complex subunit in stromal cells infiltrating the tumour acidic area." (PMID 34831016, 2021). "Studies have shown that tumour-derived IL-4, IL-5, IL-6, IL-10, and IL-13 can stimulate TAM polarization towards TAM-M2." (PMID 34141479, 2021). "Some studies identified the immunoscore of tumor tissue and serum interleukin-6 (IL-6), IL-11 or CD4+/CD8+ T cell also reflecting the immunoinflammatory status, but it is hard to be used in clinical practice due to the high cost and inconvenience." (PMID 34195071, 2021). "In the tumor microenvironment, IL-6 are mostly secreted by tumor cells as well as tumor-associated macrophages (TAMs), CD4 + T cells, myeloid-derived suppressor cells (MDSCs) and fibroblasts which directly supports tumorigenesis." (PMID 33407508, 2021). "They serve as a primary source of EMT‐inducing signaling molecules, like IL6, TNFα and TGFβ, which promote a mesenchymal phenotype of tumor cells." (PMID 34459003, 2021).
tumor (continued). "In this bidirectional crosstalk, TGF-β-containing tumor-produced EVs are able to induce the production and secretion of pro-tumor factors like IL-6 by MSCs." (PMID 34198693, 2021). "In pancreatic cancer, IL-6 not only promotes the occurrence and progression of tumours through JAK1/STAT3 but also activates reactive oxygen species through the ERK pathway." (PMID 34776511, 2021). "Inhibiting the expression of IL-6 or blocking the IL-6 pathway would alleviate tumor cell resistance to TKI therapy and enhance the antitumor efficiency of TKI, which was consistent with the founding of our study." (PMID 33582655, 2021). "The generation and activation of CAFs within tumors is at least partially mediated by inflammatory mediators and transcription factors (IL-1, IL-6, NF-κB) as part of an intensive dialogue with tumor cells." (PMID 34064859, 2021). "Recent literature data have shown that a low level of cancer tissue IL-6 improves the disease-free survival as compared with tumor counterpart tissues expressing higher IL-6." (PMID 33923292, 2021). "In summary, our work unravels an IL-6-regulated cellular mechanism that controls Mφ-mediated tumor immunity through IL-10 and Stat3/HIF-1α/CD40 expression." (PMID 34103524, 2021). "IL-6 and IL-8 secreted by CAFs can promote the differentiation of myeloid cells into MDSCs or M2 macrophages to assist tumor immune escape." (PMID 34512351, 2021). "Given the differential sensitivity of muscle and fat to the presence of tumor-derived IL-6, we sought to investigate tissue crosstalk in PDAC cachexia." (PMID 33851955, 2021). "To investigate the role of IL-6 in the immune tumor microenvironment and the response of PCa to radiation, we implemented ectopic and orthotopic tumor animal models in immunocompetent mice." (PMID 34109109, 2021). "In particular, they showed that IL-6 production can shape macrophages towards a tumor-promoting phenotype, which stimulates lymphocyte recruitment through the CCL20/CCR6 (C-C Motif Chemokine Receptor 6) axis, finally leading to CAC development." (PMID 33513730, 2021). "Interleukin 6 (IL-6) is produced by several cells such as tumour cells, adipocytes, fibroblasts, macrophages, hepatocytes and endothelial cells." (PMID 34078370, 2021). "During surgery, simultaneous increases in noradrenaline and IL-6 levels were observed, which rapidly declined after tumor removal." (PMID 34117557, 2021). "Cancer stroma fibroblasts secrete a greater quantity of IL-6 than other cancer cells and have a particular protein, aSMA protein, which has an effect on tumor growth." (PMID 34944856, 2021). "In this phase, N1 TANs exert cytolytic functions primarily through ROS production and stimulate tumor specific T cells by antigen presentation and pro-inflammatory cytokine production such as IL-1β, IL-6, TNF-α, or IL-17A." (PMID 34168563, 2021). "Our data revealed that the Pre-Tx PGSGA score was significantly correlated with the level of NLR, MDSCs and the IL-6 staining in tumor specimens." (PMID 34578883, 2021). "In esophageal squamous cell carcinoma, tumor cells activate the STAT3 pathway on NK cells through IL6 and IL8, leading to down-regulation of NKp30 and NKG2D on NK cells and tumor progression." (PMID 34447383, 2021). "Our results confirmed the findings from these studies, which concluded that higher IL-6 serum levels were correlated with the tumor stage and were inversely correlated with tumor survival and therapeutic response." (PMID 34357036, 2021). "The tumour spheroid‐formation frequencies are enhanced in the culture environment in which IL‐6 was added." (PMID 34075691, 2021). "Here, we report how tumor-NLRP3 activity promotes IL-6/STAT3 signaling in the bone marrow, which then regulates immunosuppressive gene expression in PMN-MDSCs resulting in a defunct cell population." (PMID 34531850, 2021).
tumor (continued). "It has been shown before that IL‐6 facilitates CTSB expression in monocytes in tumor tissue, suggesting a potential connection between physical activity‐induced IL‐6 levels and CTSB." (PMID 33655551, 2021). "IL-6 is produced by different cell types including stromal cells, tumor-infiltrating immune cells, and the tumor cells." (PMID 35155571, 2021). "Stress-induced IL-6- and IL-8-activated fibroblasts provide fertile soil for tumor seeds to progress and evolve." (PMID 34588424, 2021). "Apart from the inter-cellular impact, IL-6 promotes tumor invasion, agiogenesis and metastasis by enhancing the expression of a disintegrin metalloprotease 17 (ADAM17), vascular endothelial growth factor (VEGF) and matrix metalloproteinase (MMP)." (PMID 33390844, 2021). "Patients with advanced disease had higher levels of IL6, suggesting increased production by the tumor and/or by the immune effectors activated by the tumor." (PMID 35008292, 2021). "In order to test the tumor responsiveness to IL6, the expression of IL6R isoforms and IL6ST were evaluated in all TCGA tumors." (PMID 34576335, 2021). "IL-6 does not only regulate tumor growth through direct effects on tumor cells but also indirectly via the tumor microenvironment, leading to induction of apoptosis, neovascularization and acute phase responses." (PMID 34582655, 2021). "Targeting IL6/STAT3 axis represents a promising therapeutic strategy to counteract the tumor growth and invasion." (PMID 34576335, 2021). "Activated mast cells recruit tumor-associated macrophages by CSF2, CCL3, and IL-6 secretion, resulting in increased tumor growth, as shown in a gastric cancer murine model." (PMID 34063789, 2021). "Resident cells (macrophages and dendritic cells) react to tumor antigens and initiate inflammation by secreting proinflammatory mediators, such as cytokines (IL-1β, IL-6, TNF-α)." (PMID 35116038, 2021). "Several tumor-secreting cytokines, including IL-6, IL-10 and TGF-b1, are essential for Treg differentiation." (PMID 35111682, 2021). "STAT3 contributes to immunosuppression in the tumor microenvironment by the induction of immunosuppressive cytokines production in cancer cells, including IL-6, IL-8 and VEGF." (PMID 34360552, 2021). "We also demonstrate that the classical mitogen-activated protein kinase, ERK5/MAPK7, is required for IL-6 production in tumor cells." (PMID 34671021, 2021). "IL‐6‐JAK‐STAT pathway plays a significant role in the regulation of tumour immune microenvironment, and its activation is related to drug resistance of OC." (PMID 33675171, 2021). "The constant activation of the NF-κB signaling pathway in CAFs, identified in different tumors, promotes tumor progression via producing interleukin (IL)-6 and IL-8." (PMID 33731686, 2021). "Gene set enrichment analysis (GSEA) found that the tumour hallmarks of angiogenesis, IL6-JAK-STAT3 signalling, reactive oxygen species pathway and oxidative phosphorylation were enriched in high risk UM patients, consistent with disease progression." (PMID 34374416, 2021). "Recruitment of MDSC in the TME aid in this suppression of TH immune cells, where TNF-α, IL-1, IL-6, colony stimulating factor 1 (CSF-1), IL-8, IL-10, and type I interferons can also play a role in the regulation of TH immune response to tumor cells." (PMID 34012451, 2021). "These cytokines (mainly IL-6) produced by M2 cells can intensify tumor progression through regulation of the EMT process, as well as the migration and invasion of CRC cells." (PMID 33557173, 2021). "Anthracyclines induce pro-inflammatory responses by increasing tumor necrosis factor α (TNF-α), IL-1β, and IL-6, leading to tumor cell death." (PMID 35127869, 2021). "Plasma levels of IL-6 were significantly increased (∼150-fold) in KPC tumor mice over normal control levels; while mice with KPC IL6KO tumors showed increased plasma IL-6, the difference was not significantly different from shams." (PMID 33851955, 2021).
tumor (continued). "In esophagus cancer, tumor-derived signals such as IL-6, IGFBP3, and CXCL16 trigger the expansion of monocytic MDSCs with increased CD38 expression." (PMID 33727923, 2021). "In accordance with these findings observed in BM-derived Mφs, flow cytometry analysis showed that IL-6 substantially stimulated CD40 expression in tumor-derived Mφs." (PMID 34103524, 2021). "IL-23 signaling in tumor cells is important for the intra-tumoral production of downstream cytokines, which are either direct (IL-6, IL-22) or indirect (IL-17A) STAT3 activators." (PMID 33418996, 2021). "The increase of plasma cortisol and catecholamine levels modifies the distribution of circulating leukocytes leading to lymphopenia and promotes the synthesis of the pro-tumoral cytokine IL-6, hence potentially enhancing tumor progression." (PMID 35096626, 2021). "In a STAT3/ERK1,2-dependent manner, IL-6 promoted proliferation and survival of tumor cells, protected them from drug-induced apoptosis in vitro and stimulated tumor growth in vivo." (PMID 33287630, 2021). "At variance, IL-6 can also be released by various cells in the tumor microenvironment including the cancerous and stromal cells." (PMID 33216184, 2021). "By deleting IL-6 from murine tumor cells, we revealed a greater sensitivity of adipose tissue to the presence of tumor and confirmed the functional importance of tumor cell IL-6." (PMID 33851955, 2021). "Here, we provide evidence of a central role for tumor cell–derived IL-6 in mediating PDAC cachexia, and we demonstrate a novel tumor–tissue crosstalk mediated through IL-6 and sIL6R trans-signaling in the macroenvironment of the host." (PMID 33851955, 2021). "So, there seems to be a contradiction in the early tumor microenvironment regarding the change of IL-6 level." (PMID 34568032, 2021). "The results outlined that more than 60% of the total mirDIP-predicted miRNAs were significantly correlated (Pearson’s correlation value ≥ 0.3 or ≤ −0.3; p ≤ 0.05) with the expression of each gene in at least one tumor type (IL6: 67%, IL6R: 70% and IL6ST: 64%)." (PMID 34576335, 2021). "In summary, we demonstrated that chronic inflammation in the tumor environment can stimulate the activity of the IL-6/STAT3 signaling, and STAT3 can directly inhibit the transcription of miR-520f-3p." (PMID 33500736, 2021). "They observed a spurge of IL-6 along with high tumour progression in comparison to the wild-type mice when injected with TC-1 (cervical cancer) cell line." (PMID 34336101, 2021). "Macrophage-derived TNF-α and IL-1β are strong inducers of IL-6 in tumor cells, a cytokine that in turn promotes intraosseous tumor growth, osteoclastogenesis, and osteolysis." (PMID 34064859, 2021). "Tumor spread in the peritoneum and the presence of tumor cells in ascites contributed to the increase in IL-6 level." (PMID 34572929, 2021). "IL-6 can facilitate tumorigenesis by regulating tumor cell surface markers and various signaling pathways (such as metabolism, apoptosis, survival, proliferation, angiogenesis, and invasion)." (PMID 34439154, 2021). "By these efferent (from tumor to stroma) and afferent (from stroma to tumor) signaling pathways, IL-6 is one of the molecules secreted in the TME that participates in the tumor–stroma cross-talk required for tumor growth." (PMID 34360868, 2021). "Studies on CD2F1 mice inoculated with C26 cells presented an increase in the production of IL-6, IL-6R, and F4/80 (a marker for macrophages infiltration) in the heart of tumor-bearing vs. non-tumor-bearing mice." (PMID 33557173, 2021). "Total ROS levels in tumor tissue, tumor cell proliferation and hepatic levels of the proinflammatory cytokines IL-6 and TNF were reduced after chemically induced liver damage in Nox1-deficient animals." (PMID 33669824, 2021).